OR52I1 (olfactory receptor family 52 subfamily I member 1)
Description:
Odorant receptor.
Synonyms: OR11-13
Tractability: Antibody: UniProt places it where antibodies can reach, with medium confidence; UniProt predicts a signal peptide or a membrane-spanning region; its Gene Ontology location is reachable by antibodies, with medium confidence.
Gene: Protein-coding gene on chromosome 11 (4,594,039 to 4,595,013, forward strand). Ensembl gene ENSG00000232268.
Subcellular location: Cell membrane
Pathways (Reactome):
Sensory Perception: Expression and translocation of olfactory receptors
Gene Ontology:
Molecular function: olfactory receptor activity; G protein-coupled receptor activity
Biological process: detection of chemical stimulus involved in sensory perception of smell; G protein-coupled receptor signaling pathway
Cellular component: plasma membrane; membrane
Genetic constraint (gnomAD): Loss-of-function variants: 1 observed, 0.26 expected, observed/expected ratio (o/e) 3.81. That is too few expected variants to judge how well the gene tolerates losing a copy. Missense variants: 342 observed, 407.18 expected, observed/expected ratio (o/e) 0.84, 90% interval 0.77 to 0.92. Synonymous variants: 148 observed, 155.6 expected, observed/expected ratio (o/e) 0.95, 90% interval 0.83 to 1.09.
Homologues: Orthologues: chimpanzee OR52I1 (97% identical), dog OR52I1 (82% identical), mouse Or52i2 (78% identical), rat Or52i2 (76% identical). Paralogues in human: OR52I2 (95% identical), OR52B2 (45% identical), OR52E4 (42% identical), OR52E2 (41% identical), OR52J3 (41% identical), OR52K1 (41% identical), OR52K2 (41% identical), OR52B6 (41% identical), OR52D1 (41% identical), OR52E8 (41% identical), OR52E6 (40% identical), OR52E5 (40% identical), and 39 more.